LGALS17A (galectin 14 pseudogene )
Gene: Long non-coding RNA gene on chromosome 19 (39,671,807 to 39,696,913, forward strand). Ensembl gene ENSG00000291086.
Diseases named in the same sentence as LGALS17A in open-access papers:
LGALS17A is named in the same sentence as 3 diseases in open-access papers, as found by Europe PMC text mining. Sharing a sentence is not in itself a finding about the gene and the disease. The quoted sentences say what the papers report.
Obesity (1 paper, 2015). Accumulation of substantial excess body fat. "As an example of genes (rather than specific SNPs) implicated by allele-specific polysome enrichment, LGALS17A has been associated with obesity, and RAB38 in sclerosis." (PMID 26331722, 2015).
infection (1 paper, 2025). The state of being infected such as from the introduction of a foreign agent such as serum, vaccine, antigenic substance or organism. "Silencing of IRF1AS1 or ZFAS1 promoted influenza virus replication, while knockdown of PSMB8-AS1 or LGALS17A demonstrated inhibitory effects during the late infection stage." (PMID 40626712, 2025).
LGALS17A also shares sentences with these, for which no sentence is quoted: gastric cancer (1 paper).